RNU1-149P (RNA, U1 small nuclear 149, pseudogene)
Gene: Small nuclear RNA gene on chromosome 12 (22,195,469 to 22,195,629, reverse strand). Ensembl gene ENSG00000212172.
Homologues: Orthologues: chimpanzee U1 (99% identical), macaque U1 (76% identical), mouse Gm25481 (57% identical), rat U1 (57% identical), mouse Gm25728 (57% identical), pig U1 (53% identical). Paralogues in human: RNVU1-31 (77% identical), RNVU1-28 (76% identical), RNU1-1 (76% identical), RNU1-2 (76% identical), RNU1-27P (76% identical), RNU1-28P (76% identical), RNU1-3 (76% identical), RNU1-4 (76% identical), RNVU1-18 (76% identical), RNVU1-29 (76% identical), U1 (76% identical), RNVU1-7 (75% identical), and 134 more.